OR1N1 (olfactory receptor family 1 subfamily N member 1)
Description:
Odorant receptor.
Synonyms: OR1-26; OR1N3; OR9-22
Tractability: Antibody: UniProt places it where antibodies can reach, with medium confidence; UniProt predicts a signal peptide or a membrane-spanning region; its Gene Ontology location is reachable by antibodies, with medium confidence.
Gene: Protein-coding gene on chromosome 9 (122,526,358 to 122,527,293, reverse strand). Ensembl gene ENSG00000171505.
Subcellular location: Cell membrane
Pathways (Reactome):
Sensory Perception: Expression and translocation of olfactory receptors
Gene Ontology:
Molecular function: olfactory receptor activity; G protein-coupled receptor activity
Biological process: signal transduction; detection of chemical stimulus involved in sensory perception of smell; G protein-coupled receptor signaling pathway
Cellular component: plasma membrane; membrane
Genetic constraint (gnomAD): Missense variants: 384 observed, 396.81 expected, observed/expected ratio (o/e) 0.97, 90% interval 0.89 to 1.05. Synonymous variants: 130 observed, 154.57 expected, observed/expected ratio (o/e) 0.84, 90% interval 0.73 to 0.97.
Homologues: Orthologues: chimpanzee OR1N1 (99% identical), rat Or1n1 (86% identical), mouse Or1n1 (85% identical), mouse Or1n1b (79% identical), rat Or1n1b (79% identical). Paralogues in human: OR1N2 (58% identical), OR1F1 (57% identical), OR7C1 (56% identical), OR1P1 (56% identical), OR1E1 (56% identical), OR1E2 (56% identical), OR1I1 (55% identical), OR1M1 (55% identical), OR1L4 (54% identical), OR1J4 (54% identical), OR1J2 (54% identical), OR1L6 (54% identical), and 116 more.
Diseases named in the same sentence as OR1N1 in open-access papers:
OR1N1 is named in the same sentence as 1 disease in open-access papers, as found by Europe PMC text mining. Sharing a sentence is not in itself a finding about the gene and the disease. The quoted sentences say what the papers report.
cancer (1 paper, 2024). A tumor composed of atypical neoplastic, often pleomorphic cells that invade other tissues. "The list of 78 also included five encoding membrane proteins, namely SLCO6A1, ZP4, OR2C3, OR1N1, and OR4N2, which are potential pan-cancer targets for CAR-T and antibody-drug conjugates." (PMID 39561714, 2024).